RAC1 (Rac family small GTPase 1)
Diseases named in the same sentence as RAC1 in open-access papers (continued):
Sharing a sentence is not in itself a finding about the gene and the disease.
lung cancer (continued). "Based on this, the relationship between RAC1 and miR-22-3p expression in lung cancer cell lines was studied." (PMID 37620594, 2023). "In vitro, it was shown that the RHOB/PP2A/AKT1/RAC1 pathway regulates mesenchymal migration and invasion in lung cancer through implication of a PP2A-B55 complex." (PMID 37170215, 2023). "They showed that overexpressed CERS6 in lung cancer synthesizes a bioactive lipid called C16 ceramide, which activates the intracellular protein kinase, RAC1 complex." (PMID 37758931, 2023). "Our findings highlight a new axis of miR-22-3p/RAS-related C3 botulinum toxin substrate 1 (RAC1) involved in lung cancer cell migration and EMT." (PMID 37620594, 2023). "It has also been reported that deletion of p120 can inactivate RhoA but increase the activity of CDC42 and Rac1 and promote the proliferation and invasion of lung cancer cells." (PMID 35251170, 2022). "In this study, the role of Rac1 in a mice model of RILI was investigated, and the influence of regulating Rac1 expression on the development of lung cancer was explored." (PMID 35031595, 2022). "A recent study has added that ARHGEF39 is necessary for RAC1 activation during migration of lung cancer cells in response to growth factors, but this study did not investigate any potential activation of RHOA." (PMID 35959104, 2022). "For example, Rab7 expression regulated the migratory ability of lung cancer H1299 cells through Ras-related C3 botulinum toxin substrate 1 (RAC1) and vimentin." (PMID 33888099, 2021). "The long non-coding RNA LCAT1 is a competitive endogenous RNA of miR-4714-5p, which leads to the up-regulation of the activity of its endogenous target Rac1 and promotes the growth and invasion of lung cancer cells." (PMID 34079763, 2021). "Up to now, the increase of Rac1 expression has been detected in different types of cancers, such as BC, lung cancer, colorectal cancer, gastric cancer, prostate cancer, hepatocellular carcinoma and ovarian cancer." (PMID 34079763, 2021). "A high expression level of Rac1 was related to disease-free survival and prolonged survival in lung cancer patients." (PMID 34221974, 2021). "The cleavage of the hyaluronan receptor CD44 is mediated by TRAF4 via the activation of RAC1, promoting migration of A549 lung cancer cells." (PMID 33804427, 2021). "For example, GIT1 promotes the migration of lung cancer cells through activating the activity of Rac1/Cdc42." (PMID 34663332, 2021). "PP2A has been shown to regulate RhoA in T cells, and Rac1 in lung cancer, implying SET-mediated regulation of PP2A in osteoclasts." (PMID 34884920, 2021). "Deacetylmycoepoxydiene can drive Rac1 activation, promote the production of reactive oxygen species, and simultaneously induce autophagy and apoptosis in lung cancer." (PMID 34221974, 2021). "To investigate this process in vivo, we used a described previously mouse lung cancer model of Hace1 inactivation in which deletion of Rac1 and expression of oncogenic KRasG12D can be simultaneously induced by Adeno-Cre administration." (PMID 33603169, 2021). "For instance, it promotes lung cancer cell invasion and migration by modulating Rac1/Cdc42 activity." (PMID 33258389, 2021). "Overexpression of ARHGAP24 significantly inhibits the activities of RhoA and Rac1 and induced apoptosis of lung cancer cells via STAT6-WWP2-p27 axis." (PMID 34079763, 2021). "RAC1 is constitutively activated in a great majority of lung cancer and contributes critically to the development and progression of lung cancer via EMT." (PMID 32411607, 2020). "Our finding provides the evidences to explore RAC1 as a therapeutic target for radioresistant lung cancer cells." (PMID 32411607, 2020). "In this report, we provide evidence that RAC1 promoted cell proliferation and colony formation in lung cancer cells; silencing of RAC1 expression inhibited pro-survival signal of lung cancer in vivo and in vitro." (PMID 32411607, 2020).
lung cancer (continued). "The recent identification of Rac-GAP-mediated nuclear Rac1 inactivation in lung cancer cells also supports the compartmentalization of the Rac-GDP/Rac-GTP cycle." (PMID 32158759, 2020). "Considering the low frequency of alterations in Rac1 itself, then other mechanisms should be primarily responsible for the elevated Rac1 activation in lung cancer cells." (PMID 32158759, 2020). "Nonetheless, the intertwined receptor-effector networks leading to Rac1 activation in lung cancer remain ill defined." (PMID 32158759, 2020). "In this study, the function of RAC1 in human lung cancer cells and its role in response to IR were investigated." (PMID 32411607, 2020). "For example, lncRNA LCAT1 promoted tumorigenesis and metastasis of lung cancer via sponging miR-4715-5p to upregulate the RAC1 activity." (PMID 33082306, 2020). "Despite our understanding of the basis of Rac1 activation, the mechanistic foundation of deregulated Rac1 signaling in lung cancer remains poorly understood." (PMID 32158759, 2020). "The results showed RAC1 is overexpressed in lung cancer cells and promoted cell proliferation and survival." (PMID 32411607, 2020). "This perspective article will frame the highly complex mechanisms controlling Rac1 activation and their prospective clinical value to predict metastatic disease in lung cancer patients." (PMID 32158759, 2020). "In this article, we uncovered inhibition of RAC1 in lung cancer cells is sufficient to abrogate the IR-induced and RAC1-mediated tumor migration and invasion, as evidenced by cell proliferation, colony formation, and Transwell assay." (PMID 32411607, 2020). "Collectively, we further found that RAC1 enhanced radioresistance by promoting EMT via targeting the PAK1-LIMK1-Cofilins signaling in lung cancer." (PMID 32411607, 2020). "In contrast, silencing of RAC1 by sh-RAC1 contributed to the sensitivity of lung cancer cells to IR; cells transfected with sh-RAC1 also displayed decreased survival capacity by evaluating survival fraction using a colony-formation assay." (PMID 32411607, 2020). "Silencing Rac1 significantly inhibited the EMT phenotype in lung cancer cells, accompanied with a significant down-regulation of RAC1, PAK1, p-PAK1, LIMK1, p-LIMK1, Cofilin, and p-Cofilin in lung cancer cells." (PMID 32411607, 2020). "Particularly for lung cancer, Rac1 has been established as a bona fide effector of tyrosine kinase receptors (TKRs) that play prominent roles in disease initiation and progression, including EGFR." (PMID 32158759, 2020). "High expression of HSP90AA1, RAC1 and CDKN1A was significantly associated with a lower rate of overall survival in lung cancers." (PMID 32457348, 2020). "In this study, we also found that overexpression of Rac1 significantly promoted the migration and invasion, and radioresistance of lung cancer cells, whereas the knockdown of Rac1 markedly inhibited these capabilities of lung cancer cells in vivo and in vitro." (PMID 32411607, 2020). "A downside is actually the large number of upstream Rac1 activators and the limited understanding of their expression and regulation in the different lung cancer subtypes." (PMID 32158759, 2020). "In the present study, we investigated the effects of RAC1 on the survival of lung cancer cells treated with irradiation." (PMID 32411607, 2020). "It has been reported in lung cancer that RAC1 overexpression is related to the EMT process with poor prognosis." (PMID 32104177, 2020). "Here, we uncover a novel function for RAC1 signaling in the survival of lung cancer cells in response to IR, suggesting the oncogenetic roles of RAC1 in radioresistance." (PMID 32411607, 2020). "Rac1 plays fundamental roles in the control of lung cancer development, progression and metastatic dissemination." (PMID 32158759, 2020). "Our previous study demonstrated that RAC1 is closely related to radioresistance in patient samples with lung cancer." (PMID 32411607, 2020).
lung cancer (continued). "The IC50 of A549CR (carboplatin resistant lung cancer cell) decreased upon both Rac1 targeting siRNA and inhibitor treatment." (PMID 32193458, 2020). "We analyzed RAC1 expression in the RNA-seq data of lung cancer and normal tissues from the TCGA cohort." (PMID 31779616, 2019). "We also observed that lung cancer patients with normal or low copy number of RAC1 tended to have higher LCAT1 expression." (PMID 31779616, 2019). "We also quantified the expression levels of LCAT1/miR-4715-5p/RAC1 using qPCR in our lung cancer tissues." (PMID 31779616, 2019). "To determine the biological function of RAC1 in lung cancer cells, we used siRNA to knockdown RAC1 in the Calu1, A549 and HOP62 cell lines." (PMID 31779616, 2019). "For example, in lung cancer and head and neck cell carcinoma, silencing of RAC1 is related to higher cisplatin sensitivity." (PMID 31314174, 2019). "In a conditional lung cancer mouse model, RAC1 function was needed for KRAS-mediated cell proliferation and tumorigenicity." (PMID 31027363, 2019). "Rac1 overexpression is correlated with the epithelial mesenchymal transition and predicts poor prognosis in non‐small cell lung cancer." (PMID 30159893, 2019). "CCK8 and colony formation assays indicated that the knockdown of RAC1 expression significantly inhibited lung cancer cell proliferation and colony formation." (PMID 31779616, 2019). "Taken together, these data suggested that miR-4751-5p regulates RAC1 expression in lung cancer cells by directly binding to 3′ UTR of RAC1 mRNA." (PMID 31779616, 2019). "It was shown previously that Rac1 can stimulate MMP-1 production in lung cancer cell lines and enhance invasion in vitro." (PMID 30544910, 2018). "Previous studies have demonstrated that curcumin has also inhibited Cdc42 and Rac1 and prevented the migration and invasion of lung cancer." (PMID 29642589, 2018). "Depletion of Vav1 in pancreatic cancer cells and in lung cancer demonstrated a reduction in Rac1 activity." (PMID 30297765, 2018). "Our data identify a novel Cx43/EGF/ERK1/2/FAK/RhoA/Rac1-dependent signaling axis, which determines the efficiency of lung cancer cell diapedesis." (PMID 30274176, 2018). "Rac1 can stimulate MMP-1 or MT1-MMP production in lung cancer cell lines and enhance invasion in vitro." (PMID 30544910, 2018). "For example, PIKfyve promotes cell migration and invasion through activation of Rac1 in lung carcinoma, osteosarcoma or rhabdomyosarcoma cells, while inhibition of PIKfyve resulted in a significant decrease in cell migration velocity and persistence." (PMID 30445978, 2018). "In lung cancer, ITSN-1s deficiency shifts the balance in favor of greater Eps8-Sos1 interaction and less Eps8-Cbl interaction leading to activation of Rac1 and increased expression of Eps8 respectively." (PMID 28874189, 2017). "EL decreased phosphorylation of FAK and its downstream targets, Src, paxillin, and decreased mRNA expression of cell motility-related genes, RhoA, Rac1, and Cdc42 in lung cancer cells." (PMID 28068967, 2017). "In the presence of ITSN-1s, decreased Rac1 activation and reciprocal upregulation of RhoA shift the balance in favor of decreased lung cancer cell migration and metastasis." (PMID 28874189, 2017). "In lung cancer, ITSN-1s deficiency impairs Eps8 ubiquitination and favors Eps8-mSos1 interaction which activates Rac1 leading to enhanced lung cancer cell proliferation, migration and metastasis." (PMID 28874189, 2017). "Some researches demonstrated that Rac1 is involved in the metastasis and angiogenesis of lung cancer." (PMID 27556698, 2016). "Specifically, activated Rac1 regulates tumor invasion of lung cancer cells by regulating gene transcription of MMP2 and MMP9." (PMID 27164951, 2016). "Next we examined the Spearman's rho correlation to determine the GIT1 and Rac1/Cdc42 correlation in our lung cancer cohort." (PMID 26462147, 2015).
lung cancer (continued). "Our results suggest that GIT1-mediated regulation of lung cancer cell motility depends, at least in part, on its ability to modulate Cdc42 and Rac1 activity." (PMID 26462147, 2015). "GIT1 expression increased lung cancer cell invasiveness through Rac1/Cdc42 activity and promoted tumor growth and metastasis in vivo." (PMID 26462147, 2015). "Recent studies in pancreatic cancer and lung cancer cells that express Vav1 showed that Vav1 functions as a GEF for Rac1 GTPase following EGF stimulation and that this activity is critical for its function." (PMID 23342133, 2013). "The CXCR4/C-X-C motif chemokine ligand 12 (CXCL12) signaling axis regulates lung cancer cell migration through the activation of Ras-related C3 botulinum toxin substrate 1 (RAC1), MMPs and multiple signaling pathways, including extracellular regulated protein kinase (ERK) and NF-κB." (PMID 41429896, 2025). "RAC1 and ERBB3 have been reported to be associated with drug resistance in lung cancer." (PMID 39338283, 2024). "Inhibition of migration and invasion of lung cancer cells via Rac1/PAK1 signaling pathway." (PMID 37191432, 2023). "Increased RAC1 activity has been associated with TKI resistance and lung cancer metastasis." (PMID 37051524, 2023). "RAC1 is a target of many miRNAs in various cancers, such as miR-194-5p in osteoclasts, miR‐142‐3p in colorectal cancer, and miR-509-3p in cervical cancer, miR-4715-5p in lung cancer." (PMID 37620594, 2023). "Scratch wound healing test showed that activated RAC1 could enhance the migration ability of lung cancer cells in the plate (P < 0.01 for H1975; P < 0.05 for A549)." (PMID 37202394, 2023). "LCAT1 has been found to regulate the function of RAC1 by sponging miR-4715-5p in lung cancer." (PMID 37355516, 2023). "Moreover, RAC1 signaling has been shown to promote EMT in lung cancer, as well as resistance to chemotherapy and targeted therapies in several cancers." (PMID 37748077, 2023). "In our study, comparing MYADM with other known lung cancer biomarkers by bioinformatic methods, we found MYADM was associated with ICAM1 and RAC1, suggesting that MYADM may be a prognostic factor for NSCLC." (PMID 36061144, 2022). "Previous studies have shown that vimentin regulates cell-ECM association by controlling the size of focal adhesions through interacting with integrin β1 and β3, vimentin also increases lung cancer cell adhesion by stabilising FAK-positive focal adhesions through activating Rac1." (PMID 36552797, 2022). "We then investigated whether effects of IR on invasion and migration were mediated by RAC1 expression in lung cancer cells." (PMID 32411607, 2020). "These evidences strongly indicate that RAC1 contributes to lung cancer progression and maybe a useful prognostic biomarker of lung cancer." (PMID 32411607, 2020). "Furthermore, the reliance of KRAS on Rac1 in lung cancer development also predicts Rac-GEFs as KRAS effectors, also potentially via a PI3K-dependent mechanism." (PMID 32158759, 2020). "The reported anti-tumor effect of Rac1 and Pak1 inhibitors in lung cancer models and the evidence for enhanced Pak1 activation in lung cancer are strong indicators of Rac1 hyperactivation." (PMID 32158759, 2020). "Overexpression of RAC1 has been detected in the great majority of lung cancers." (PMID 32411607, 2020). "We then examined the biological function of RAC1 in lung cancer cells." (PMID 32411607, 2020). "Furthermore, RAB7A is able to regulate cell migration through Ras-related C3 botulinum toxin substrate 1 (RAC1) and vimentin in human lung cancer NCI H1299 cells." (PMID 31374919, 2019). "Our findings suggest that the LCAT1-miR-4715-5p-RAC1/PAK1 axis could be a valuable target for lung cancer prognosis and therapies." (PMID 31779616, 2019). "Consistent with our hypothesis, we found that RAC1 expression was upregulated in lung cancer tissues compared to normal tissues." (PMID 31779616, 2019).
lung cancer (continued). "To further determine whether RAC1 is regulated by miR-4715-5p in lung cancer cells, we measured RAC1 mRNA and protein levels in lung cancer cells with depletion or overexpression of miR-4715-5p." (PMID 31779616, 2019). "The results demonstrated that RAC1 is significantly upregulated in lung cancer tissues." (PMID 31779616, 2019). "LCAT1–miR-4715-5p–RAC1/PAK1 axis plays an important role in the progression of lung cancer." (PMID 31779616, 2019). "Interestingly, increased copy number was observed at the RAC1 locus in lung cancer, which consequently upregulated its mRNA expression." (PMID 31779616, 2019). "For example, in lung cancer, silencing of RAC1 is related to an increase in chemosensitivity." (PMID 31314174, 2019). "To investigate whether miR-182/CTTN is involved in regulating Rac1 and ROCK by modulating invadopodia formation in lung cancer cells, we measured the protein levels of Rac1 and Rock1." (PMID 29986736, 2018). "This is significant as Rac1 and vimentin are essential regulators of the cytoskeleton structure with control over the epithelial-mesenchymal transition, cell migration and metastasis of lung cancer." (PMID 30333761, 2018). "In addition, the IF protein vimentin, VAV2, and Rac1 interact in the regulation of the invasive capacity of lung cancer cells by controlling the formation of focal adhesions via FAK." (PMID 29152145, 2017). "Additionally, similarly to Rac1, Rac1b is also required for K-Ras-induced lung cancer in transgenic mouse models." (PMID 27442895, 2017). "Although the inverse activity relationship between Rac and RhoA remains to be established, both Rac1 and RhoA activation seems to exist in Crk overexpressing lung cancer cells through Dock families or other molecules such as Src, Fak, and Abl those can be activated by Crk." (PMID 27027347, 2016). "Although curcumin inhibits lung cancer cell migration and invasion via Rac-1 or Wnt/B-catenin pathways, the regulatory mechanism of curcumin in lung cancer remains unknown." (PMID 26656720, 2015). "Hence, by using in vitro co-culture and in vivo endothelial Rac1 knockout mouse approaches, we have investigated the potential roles of Rac1 in hematogenous metastasis of lewis lung carcinoma cells (LLC) to lung." (PMID 25991673, 2015). "Recent studies in pancreatic cancer and lung cancer cells showed that ectopically expressed Vav1 acts as an upstream activator of Rac1, RhoA and possibly Cdc42 signaling pathways in response to extracellular stimulation, leading to cytoskeleton changes in cancer cells." (PMID 23342133, 2013). "Rac1 activity can influence cell cycle progression and survival, and it was shown to be required in K-ras mediated lung tumor growth in a murine spontaneous lung cancer model." (PMID 21347385, 2011). "We found that δ-catenin overexpression caused a significant increase in the proliferation rate, colony formation and invasion ability of U251 cell lines, with a significant increase in Rac1 activity, which was in accordance with our previous results for lung cancer." (PMID 22151302, 2011). "It was reported previously that Rac1 was required for K-RasG12D-induced lung cancer." (PMID 21358804, 2011). "The phalloidin staining results showed that RAC1 inhibitor could significantly inhibit the expression of polymeric actin in lung cancer (P < 0.01), and RAC1 agonist agent could significantly promote the expression of polymeric actin in lung cancer cells (P < 0.05)." (PMID 37202394, 2023). "Moreover, RAC1 protein expression in the lung cancer cell lines was measured with Western blot." (PMID 37620594, 2023). "Interestingly, in NSCLC, RAC1 is required for oncogenic KRAS-induced lung cancer in mice." (PMID 37748077, 2023). "Rac1 is a kind of vital small Rho GTPases family protein and Rac1-regulated actin cytoskeleton rearrangement may play a crucial part in the anti-invasion of curcumin on lung cancer cells." (PMID 37191432, 2023).